CTSB (cathepsin B)
Diseases named in the same sentence as CTSB in open-access papers (continued):
Sharing a sentence is not in itself a finding about the gene and the disease.
tumor (continued). "Tumor cell knockdown of cathepsin B significantly abrogated metastasis to lung and bone." (PMID 26308073, 2015). "Also, by increasing our understanding of the role played by ECM components in the tumor microenvironment and their potential impact on protease inhibition, we can provide more reliable data for further assays searching for CTSB inhibitors in cancer tumors." (PMID 26562785, 2015). "The interspersed CTSB +ve and −ve areas will require further analysis of a larger cohort in correlation with histopathology in order to determine the value of biomarker mapping in detecting tumor margin." (PMID 26197973, 2015). "Likewise, enforced tumor cell expression of an endogenous cysteine cathepsin inhibitor, Stefin A, had similar effects, as did systemic treatment with a small-molecule cathepsin B inhibitor, CA074." (PMID 26308073, 2015). "In contrast, down-regulation of Cathepsin B using siRNA significantly inhibited the invasion, migration and adhesion of Tca8113 cells overexpressing EMMPRIN-2, implicating the functional importance of Cathepsin B in EMMPRIN-2-mediated signaling for tumor invasion and metastasis." (PMID 24705283, 2014). "CTSB immunoreactivity in the tumor cells was noted to be 95.7%." (PMID 25050350, 2014). "In addition, they found that cathepsin B was highly expressed in tumor cells with an emphasis on the hypoxic pseudopalisading cells surrounding necrotic areas." (PMID 24743710, 2014). "Furthermore, membrane-bound CtsB was detected on PyMT tumor cells by using a cell surface labeling approach[6d] with biotinylated inhibitor NS-196." (PMID 24975267, 2014). "As a lysosomal cysteine endoproteinase, CTSB can degrade laminin, fibronectin, collagen, and other extracellular matrix components, and promote the formation of tumor blood vessels; therefore, it is believed to be one of the key enzymes in invasion and metastasis of malignant tumors." (PMID 24717913, 2014). "It was suggested that Cat X, not being dependent on the degradation of extracellular matrix, a typical event for cathepsin B, may compensate the malignant effects of cathepsin B by changing the migration mode of tumour cells." (PMID 24725597, 2014). "Cathepsin B is found at the tumor invasive border supporting its importance for tumor spread." (PMID 23577028, 2013). "However, the CTSB-shRNA significantly inhibited tumor metastases and prolonged survival in LL/2 metastatic model." (PMID 24139065, 2013). "Moreover, although many constructs have been designed for intratumoural activation, particularly intralysosomal drug release (using low pH or lysosomal enzymes such as cathepsin B), few tumour models are calibrated with respect to these activation mechanisms." (PMID 23797686, 2013). "Furthermore, NO activation of Ets-1 resulted in increased expression and activity of proteases critical for tumor metastasis, MMPs and CTSB, and resulted in increased cancer cell invasion and proliferation." (PMID 22971289, 2012). "Moreover, CTSB was identified in the cytoplasm of tumor cells showing different pattern from staining with anti-PCNA antibody in which PCNA was identified in nucleus." (PMID 20727192, 2010). "In addition to CTSB, other CTSs have been proposed as participants in the angiogenesis and invasion of tumor cells." (PMID 20727192, 2010). "A role of CTSB in tumor cell invasion was suggested by the increased invasiveness of cells overexpressing CTSB and by decreased invasion in the presence of specific inhibitors of CTSB." (PMID 20727192, 2010). "For instance, numerous clinical studies have hypothesized a correlation between extralysosomal cathepsin B expression and release with neoplastic disease progression and clinical outcome." (PMID 20684763, 2010). "Inhibition of cathepsin B could possibly lead to changes of tumor microenvironment, to a decreased cell survival and spreading and, therefore, to the impairment of metastatic seeding and onset." (PMID 20684763, 2010).
tumor (continued). "The possibility that cathepsins, including cathepsin B, could play a key role in the formation of acidic tumor microenvironment should also be taken into account." (PMID 20684763, 2010). "Cathepsin B influences tumor microenvironment by degradation of extracellular matrix and by activation of other proteolytic enzymes such as pro-urokinase-type plasminogen activator (pro-uPA) and matrix metalloproteases (MMPs) so that tumor cells can actively invade and metastasize." (PMID 19956729, 2009). "Cathepsin B, secreted by invading tumor cells, can degrade collagen and elastin." (PMID 15642138, 2005). "Moreover, CystC-mediated cathepsin B inactivation will reduce the activity of the urokinase plasminogen system, which enhances tumor cell extracellular matrix degradation, as well as growth factor and latent TGF-β activation." (PMID 16168131, 2005). "was injected i.v. into C57 mice bearing subcutaneously (s.c.)palpable B16F10 tumours followed after 5 h by HPMA copolymer-cathepsin B there was a rapid increase in the rate of dox release within the tumour (3.6-fold increase in the AUC compared to that seen for PK1 alone)." (PMID 11592781, 2001). "In mice bearing the MAC16 tumour, there were increases in both cathepsin B and L, and the Ca2+-dependent lysosomal and ATP-dependent pathways were found to contribute to the increased proteolysis; whereas, in PIF-injected animals, there was activation only of the ATP-dependent pathway." (PMID 9764574, 1998). "Although tumor-associated proteolytic activation in vivo is indicated, this does not contribute to tumor retention as judged from control experiments under pharmacological blockade of cathepsin B and with nonfunctional analogues." (PMID 41988367, 2026). "However, during tumor development, the regulation of cathepsin B may suffer disturbances at different stages, leading to its excessive expression and subsequent release into the extracellular space." (PMID 38590662, 2024). "Cathepsin B (CTSB) is a cysteine protease presentin lysosomes that is highly expressed in a variety of tumors, andwhen excreted it can degrade extracellular matrix components, suchas collagen, laminin, or tenascins, thereby promoting tumor invasionand metastasis during cancer progression." (PMID 38422393, 2024). "CTSB acts via 3 isoforms: main transcript, main transcript lacking exon 2 or main transcript lacking exon 2 and 3.Its functions may encompass the regulation of angiogenesis, invasion, tumor proliferation, immune resistance, and cell differentiation." (PMID 39264885, 2024). "Theoretically, the GFLG sequence in agent 13 might be cleaved by cathepsin B overexpressed in tumours after being transported to cancer cells with overexpressed αvβ3 integrin receptors, resulting in an enhanced fluorescence signal output concurrent with activated photoactivity for image-guided PDT." (PMID 38999115, 2024). "Moreover, the TME can regulate CTSB expression in tumor cells and other tumor-associated cell types (including stromal fibroblasts and inflammatory cells), and stromal cells of the TME are the main source of CTSB expression." (PMID 37576397, 2023). "First, premature cleavage of the ADC linker by tumor cells, tumor-associated macrophages, or other sources of cathepsin B may result in systemic toxicity through the nonspecific release of the warhead before it can be internalized by the target cell." (PMID 37355629, 2023). "In such a contest, cathepsin B cysteine protease overexpressed in tumors, has been largely employed to activate prodrugs fused to carrier macromolecules throughout the recognition of a cleavage site, leading to the accumulation of the active cytotoxic compound in tumor cells." (PMID 36579638, 2023). "In addition, the potential role of CTSB in non-neoplastic diseases was discussed." (PMID 37576397, 2023).
tumor (continued). "CTSB can also bind annexin A2 on the cell surface 115 and is involved in the activation of binding proteins in discrete regions of the extracellular space, which may explain the role of CTSB in tumor invasion and metastasis." (PMID 37576397, 2023). "Cathepsin B, for instance, which performs as an extracellular matrix protein, could affect cellular processes like angiogenesis as well as metastasis and have an impact on tumor growth, migration, and invasion." (PMID 37334378, 2023). "However, PGA may be digested by cathepsin-B, which is released into the tumor microenvironment of most solid tumors and is lysosomal protease cathepsin-B." (PMID 35903701, 2022). "Interestingly, a negative correlation between the expression of these proteins was detected comparing tumor CTSB expression and healthy tissue STFA expression: a higher CTSB mRNA content in tumors was accompanied by a lower STFA mRNA level in paired non-tumor samples." (PMID 35563761, 2022). "However, the solutions may come from combination approaches that target uPAR concomitantly with uPA, MMP, cathepsin B and other molecules to increase cancer therapy sensitivity and suppress tumor growth and metastasis." (PMID 35205745, 2022). "Additionally, CTSB may play a role in tumor initiation, proliferation, angiogenesis, and metastasis, and promote carcinogenesis in pancreatic tissue." (PMID 35872750, 2022). "The results demonstrated that digestion of the formulation with cathepsin B resulted in the reduction of nanoparticle size and overall negative charge, potentially leading to more efficient diffusion of the nanoparticles throughout impermeable tumour tissues following extravasation." (PMID 33245955, 2021). "Indeed, PGA is biodegradable by cathepsin B, which is highly expressed in tumor tissues." (PMID 33855017, 2021). "However, the migration potential was significantly inhibited by CA074, the inhibitor for Cathepsin B (Lenti-CCNB2+CA074 vs. Lenti-CCNB2: 47.9±5.57 vs. 69.5±3.91%, P=0.005), which suggested that Cathepsin B secreted from CCNB2-related senescent cells promoted tumor migration." (PMID 34512164, 2021). "Therefore, increased CREG1 levels in tumor-bearing CTSB or CTSB/CTSZ knock-out mice could mediate the reduction in tumor proliferation and invasive growth that has been consistently reported for such models." (PMID 32385587, 2021). "Thus, CTSB knockdown attenuates tumor growth of HL-60 cells in vivo." (PMID 33628106, 2021). "In vitro, sustained TGF-β treatment induced cathepsin B (CTSB)-mediated degradation of Disabled-2 (Dab2), which activated autophagy and inhibited apoptosis by destabilizing the pro-apoptotic Bim protein, thereby modulating doxorubicin-resistance and tumor metastasis." (PMID 34917620, 2021). "Cathepsin B (CTSB), a lysosomal cysteine protease, is a member of the cysteine protease family, and experimental models have shown that it has a central role in multiple pathologic processes, including initiation, tumor cell proliferation, growth, angiogenesis, and metastasis." (PMID 33333840, 2020). "In addition, cathepsin B is considered to be involved in proteolytic cascade destruction of the extracellular matrix, which further remodels the tumor environment by enabling angiogenesis, tumor migration, invasion, and even metastasis." (PMID 32999282, 2020). "Additionally, CATB (Cathepsin B) was previously reported as a potential candidate cancer biomarker in HCC, HPT (haptoglobin) was reported to associate with tumor progression in HCC, while POSTN (periostin) was reported as a marker for malignant transformation of hepatocytes." (PMID 30598095, 2018). "Due to its potent but reversible inhibition of cathepsin B endopeptidase activity, together with the improved selectivity for cathepsin B with regard to related peptidases cathepsins H and L, compound 17 was chosen for further evaluation of its anti-tumor activity in vitro and in vivo." (PMID 28938624, 2017).
tumor (continued). "Additionally, the incidence of CTSB protein expression in well-differentiated carcinoma was significantly lower than that in poorly differentiated tumors, and CTSB expression was significantly related with tumor differentiation (P = 0.003)." (PMID 26896959, 2016). "In addition, many proteases such as cathepsin B are highly expressed in tumor tissues, which may help cleave the chemical bond between the prosthetic group and the polymers to release free drug (e.g., ZnPP)." (PMID 28031879, 2015). "In addition, cathepsin B seems to be localized in the perinuclear region of tumor cells and, consequently, the cellular distribution of heparan sulfate associated with growth factors may also have been altered." (PMID 25351637, 2015). "However, some proteins we found differed from previously identified proteins (Such as ANXA4, CFHR2, CHP, CTSB and so on), which may result from ethnic differences or tumor heterogeneity." (PMID 24139065, 2013). "The co-enrichment of CTSL and CTSB, in conjunction with elevated NRP1 levels, contributes significantly to angiogenesis and tumor invasion, marking the progression from a healthy state to the development of ccRCC." (PMID 40134439, 2025). "HQ-30 targets cathepsin B (CTSB) to mediate PD-L1 degradation, which leads to increased infiltration of CD4+ T cells and CD8+ T cells in tumors, thereby reshaping the tumor microenvironment." (PMID 40006729, 2025). "To explore this, we rationally designed and synthesized a tumor-selective prodrug, H62, by conjugating our potent DHODH inhibitor EA6 with the validated STING agonist MSA-2 (MSA) via a cathepsin B (CTSB)-cleavable linker." (PMID 41239499, 2025). "Inhibitors like CA-074 (cathepsin B), PI-88 (heparanase), and various integrin and LOX antagonists have shown potential to suppress tumor growth and proliferation in preclinical models." (PMID 40871003, 2025). "Upregulated CTSB can proteolytically degrade the ECM components including collagen I, collagen IV, fibronectin, and laminin, to drive tumor cell invasion." (PMID 40007784, 2025). "It leads to the enhancement of O-GlcNAcylation on cathepsin B in TAMs, which in turn leads to increased secretion of cathepsin B in the TME and promotes tumor metastasis." (PMID 40131539, 2025). "Even though they exhibited consistent tumor-normal dysregulation, five genes (COL12A1, CTSB, PLOD1, SPP1, and SULF1) were excluded from the final candidate list as they did not satisfy the meta-analysis criteria and exhibited loss of prognostic significance." (PMID 41451347, 2025). "In particular, cathepsin B is a crucial regulatory protein in different types of cell death, and its overexpression contributes to GBM angiogenesis and tumor progression." (PMID 40535571, 2025). "After internalization by tumor cells, PROTAC were released intracellularly by cleavage of cathepsin B in lysosomes." (PMID 39419977, 2024). "Cathepsin B assumes a multifaceted role within the TME, influencing diverse facets of tumour progression and interactions with the surrounding microenvironment." (PMID 38500921, 2024). "The BPGP@CAP nanoassembly enables targeted delivery of both PTX and CAP into the tumor site through the EPR effect, and precise release of PTX and CAP from BPGP@CAP after intelligently responding to overexpressed cathepsin B in the lysosomes of tumor cells." (PMID 37953442, 2024). "Research reveals the upregulation of cathepsin B in HCC tissues, where it is released by tumour cells, thereby promoting migration and invasion within the context of HCC." (PMID 38500921, 2024). "After entering the tumor cells, HA-BPY-GEF-NPs remained in an active state within cathepsin B–abundant lysosomes." (PMID 39321294, 2024). "Upregulated cathepsin activity (CTSB, CTSD, and CTSZ) and complement pathway (C1QA, C1S) indicated pro-tumor activity by the TAMs in this region." (PMID 38217035, 2024).
tumor (continued). "Cathepsin B, a lysosomal cysteine protease, emerges as a critical player in OSCC, influencing tumour initiation, invasion, and metastasis." (PMID 38500921, 2024). "Moreover, cathepsin B's involvement in tumour-stromal interactions is apparent, as these interactions induce the expression of cathepsin B. The TME also witnesses the release of cathepsins, which may interact with pericytes, versatile mural cells within the TME." (PMID 38500921, 2024). "The simultaneous delivery of both imatinib and curcumin via nanomaterials induces the release of CTSB from lysosomes, elicits LMP, and promotes cell death, therefore enhancing tumor cell sensitivity to imatinib." (PMID 37484013, 2023). "Clinically, the tumor expression between miR-218-1-3p and BMI1/CTSB is negatively correlated in HCC patients." (PMID 37923799, 2023). "By performing a florescence in-situ hybridization (FISH) experiment of miR-218-1-3p with HCC tumor sections, we showed that in HCC tumors, the expression level of miR-218-1-3p was correlated negatively with BMI1/CTSB expression respectively." (PMID 37923799, 2023). "Both linkers can be selectively cleaved by cathepsin B proteases within CCA cell endosomes/lysosomes, providing clinically-validated therapeutic benefits in treating tumor microenvironments via bystander killing effects." (PMID 37717087, 2023). "Elevated CTSB activity, which results in increased secretion or mobilization of VEGF, enhances the induction of tumor angiogenesis." (PMID 37576397, 2023). "In the spatial transcriptome, it is clear that BARD1 expression is overall low, while CTSB and GSTP1 are mainly expressed in the core region of the tumor." (PMID 37727789, 2023). "An imbalance between CTSB and cystatin C regulation is critical for the degradation of ECM components, leading to various phenomena, such as tumor metastasis." (PMID 37576397, 2023). "Inhibition of uPAR and cathepsin B can inhibit the angiogenesis around tumor cells by reducing JAK/STAT-dependent VEGF expression and impairing tumor invasion ability." (PMID 37398678, 2023). "Cathepsin B cleavage site introduced between CD9/CD81 and RFP was recognized by tumor specific proteases allowing the release of the reporter protein." (PMID 36579638, 2023). "In vitro studies revealed a functional role of upregulated cathepsin B in pericellular proteolysis of the ECM and basement membrane components, driving tumor invasion." (PMID 36002710, 2023). "Inhibition of Cathepsin-B O-GlcNAcylation impairs metastasis of cancer cells, indicating a critical role of OGT and O-GlcNAc in remodeling the tumor microenvironment to support invasion and metastasis." (PMID 37838167, 2023). "Biochemical studies have identified that collagen I, collagen IV, fibronectin, and laminin can be substrates of CTSB, and CTSB can proteolytically degrade these ECM components and drive tumor cell invasion." (PMID 37576397, 2023). "TAMs secrete CTSB, CTSL, and CTSS and therefore, TAMs also provoke tumor growth, angiogenesis, invasion, and metastasis responses." (PMID 36289617, 2022). "We also stained tumor sections for the core MI components COMP, FN1, CTSB, and VCAN, which were transcriptionally upregulated in PKN2KO tumors; stains were enhanced in invasive regions and in regions of connective tissue." (PMID 35081338, 2022). "In contrast to CTSD and CTSB stimulating apoptosis, CTSS actually inhibits apoptosis and thereby promotes tumor progression." (PMID 36289617, 2022). "TF peptide guides the nanoparticle to TfR overexpressing malignant tumor cells and cathepsin B control the release of ART and buthionine-sulfoximine to increase ROS production, decrease GSH levels and thus induce tumor cell death." (PMID 35214127, 2022). "The tumor-specific MMAE prodrug nanoparticles, FRRG-MMAE, constructed with cathepsin B-specific cleavable FRRG (Phe-Arg-Arg-Gly) peptide and MMAE, were designed to reduce the severe MMAE-related toxicity and to enhance their antitumor efficacy." (PMID 36297566, 2022).